HES1 (hes family bHLH transcription factor 1)
Diseases named in the same sentence as HES1 in open-access papers (continued):
Sharing a sentence is not in itself a finding about the gene and the disease.
breast carcinoma (continued). "Hes1 shows a positive correlation with CSC markers (such as CD133, CD44, SOX2, Nanog, etc.)in colon, gastric, and breast cancers." (PMID 40755759, 2025). "Our study utilized Western blot and RT-PCR assays to test the expression of Hes1 and Hey1 treatment with LAQ in colorectal and breast cancer cell lines." (PMID 37686467, 2023). "On the other hand, TCF7L2, ARRB1, DLL1, FZD7, HES1, and JAG1 transcript levels were significantly lower in breast cancer tissues than in normal samples (p < 0.0009, p = 0.0131, p = < 0.0001, p = < 0.0001, p = 0.0138, and p < 0.0001, respectively)." (PMID 36476410, 2022). "Hypoxia enhanced the expression of Notch target genes HES1 and HEY1 in different breast cancer cells." (PMID 36476410, 2022). "These genes were also enriched in the PI3K/Akt, Notch1/Hes1 or Akt1/mTOR signaling pathways and were reported to be correlated with LNM in breast cancer." (PMID 36644636, 2022). "In breast cancer cells, it was shown that repressing the 17β-estradiol- and heregulin-β1-mediated up-regulation of E2F1 was induced by HES1." (PMID 36012128, 2022). "The upregulation of Hes1, Met, and Mecom in the mammary gland by exposure to PFOA + ZAL at the doses we used may not be enough to induce mammary tumorigenesis in rats, but it may contribute to the increased mammary tumor susceptibility when challenged with a carcinogen such as DMBA." (PMID 35163327, 2022). "The expression levels of breast cancer stem cell markers, such as CD44 and Nanog33,43,44, as well as the expression levels of Jagged-1 and Hes1, were increased in BMP-4-treated MDA-MB-231 cells, compared to control cells." (PMID 31409851, 2019). "Nrf2‐dependent G6PD/HIF‐1α activation provokes Notch1 signalling by up‐regulation of Jagged1 and Hes1, thereby promoting EMT in breast cancer cells." (PMID 30809937, 2019). "By gain‐ and loss‐of‐function assays, we show that depletion of Furin in Plac1‐overexpressing breast cancer cells attenuated the Plac1‐induced expression of NICD, HES1, MMP2, and MMP9 and tumor cell invasion and metastasis." (PMID 29704427, 2018). "The study also evaluated the influence of the ADAM10, NOTCH1, NOTCH3, HES1, LFNG and PSEN1 genes on breast cancer recurrence." (PMID 27888801, 2017). "MRP1, Hes1 and Hey1 expression were all also increased after doxorubicin treatment in the MCF7 breast cancer cell line." (PMID 26362310, 2015). "Hypoxia increased the expression of Notch target genes such as HES1 and HEY1 in breast cancer cells, as was expression of Notch receptors and ligands." (PMID 20010940, 2010). "Our study found that the expression of Notch target genes HES1 and HEY1 was increased in most breast cancer cells with hypoxia." (PMID 20010940, 2010). "Hypoxia-induced Notch activation promotes EMT in breast cancer cells, as shown by increased expression of Notch targets HEY2 and HES1, downregulation of E-cadherin and β-catenin, and increased cell migration and invasion of breast cancer cells cultured in low-oxygen conditions." (PMID 33003540, 2020). "MMPs, ADAMs, HES1/2, HEY1, c-Myc, CD44, EpCAM and Vimentin (downregulation of E-cadherin) engage in survival, stemness, EMT, invasion, ECM degradation/remodeling, angiogenesis, intravasation/extravasation, and metastatic colonization in breast cancer." (PMID 31694640, 2019). "Hairy and enhancer of split-1 (HES1) response elements were also found within the miR-205-5p promoter, and exert a negative effect on miR-205-5p expression in breast cancer." (PMID 31752366, 2019). "Intriguingly, Notch2 and its ligand, Jagged-1, could also upregulate HES1 expression to inhibit miR-205-5p, and constituted a negative feedback loop of Notch2/miR-205-5p/ZEB1 signaling in breast cancer cells." (PMID 31752366, 2019). "Moreover, we demonstrated that selected genes from this subset (HES1, PRKCH, ELF5 and TM4SF1) did support invasiveness in ER+ breast cancer cells." (PMID 26356672, 2015).
breast carcinoma (continued). "γ-secretase inhibitor (GSI) treatment inhibited the binding of NOTCH3/MAML1 complex to HES1 promoter, indicating that Notch pathway is active in these breast cancer cells and MAML1 might be a co-activator of Notch signaling in breast cancer." (PMID 20010940, 2010). "In breast cancer and colorectal cancer cells, lycopene significantly downregulates the expression of Notch1 and its ligand Jagged1, blocks nuclear translocation of the NICD, and subsequently suppresses Hes1 expression, leading to inhibition of cell proliferation and induction of apoptosis." (PMID 41602823, 2026). "The overexpression of Hes1 is significantly associated with advanced TNM staging, lymph node metastasis, and estrogen receptor (ER)-negative status, suggesting its critical role in breast cancer progression and metastasis." (PMID 40755759, 2025). "Although HES1 is associated with triple-negative breast cancer and MET is associated with basal cancer in humans, out of 493 mammary tumors analyzed, we only found one ER-alpha-negative tumor from the PFOA + ZAL group; all others were ER-alpha- and PR-positive." (PMID 35163327, 2022). "However, 6-shogaol induces autophagic cell death in breast cancer cells and CSC-like spheroids via γ-secretase mediated down-regulation of Notch signaling (reduction in the expression levels of cleaved Notch1 and its target proteins Hes1 and Cyclin D1)." (PMID 34575981, 2021). "Real-time quantitative PCR analysis revealed decreases in Hes1, Deltex1, and c-Myc expression levels in tumors isolated from dox-treated mice compared with untreated controls, thereby confirming repression of NOTCH1 signaling in the dox-treated mammary tumor-bearing mice." (PMID 22992387, 2012). "The expression of Notch target genes such as HES1 and HEY1 were increased in MCF7 cells and MDA-468 cells when they were cultured at 1% O2 condition, indicating that hypoxia, presumably through induction of HIF factor expression, regulates Notch signaling in breast cancer cells." (PMID 20010940, 2010). "However, despite several attempts to investigate Hes-1 expression in breast cancer, we have not found any difference in Hes-1 expression in breast cancer tissues compared with normal tissues." (PMID 19891787, 2009). "Interestingly, when we analysed existing clinical breast cancer cohort data, we found that the high expression level of HES5, but not HES1 or HEY1 was significantly correlated with a poor brain metastasis-free survival of breast cancer patients." (PMID 23495140, 2013). "However, the increased HEY1 expression by hypoxia was more dramatic compared with HES1 expression, indicating HEY1 might be a better marker of Notch activation in breast cancer cells." (PMID 20010940, 2010).
glioma (39 papers, 2012 to 2026). A benign or malignant brain and spinal cord tumor that arises from glial cells (astrocytes, oligodendrocytes, ependymal cells). "Previous studies have reported that Hes1 overexpression was associated with poor survival of patients with glioma and medulloblastomas." (PMID 26452025, 2015). "In gliomas, tigecycline suppresses Hes1 via miRNA-199b-5p, inhibiting PI3K/AKT signaling while elevating p21 to induce cell cycle arrest." (PMID 40755759, 2025). "In glioblastoma, miR-139 inhibits Notch1/Hes1, thereby suppressing the activation of the Wnt/β-catenin pathway, thus inhibiting glioma stem cell stemness and tumorigenesis." (PMID 40755759, 2025). "Similar published results showed that Tigecycline inhibited glioma cell growth in an in vitro study by regulating the miRNA-199b-5p-HES1-AKT pathway." (PMID 39315277, 2024). "The poor expression of miR-524-5p was also documented in glioma, and miR-524-5p overexpression restrained glioma cell proliferation by targeting Jagged-1 or Hes-1 in vitro." (PMID 35635748, 2022). "Various studies have demonstrated increased expression of distinct components of Notch signaling pathway (such as Notch1, Notch2, Dll1, Dll4 and Jag1) and Notch target genes (Hey1, Hey2, Hes1) in glioma cell lines or primary human glioma samples including GBM." (PMID 36010607, 2022). "Next, we investigated the involvement of integrin-FAK-JAG1-Notch-HES1 signaling in FMOD-induced angiogenesis in the context of glioma tumors." (PMID 35642785, 2022). "ZFAS1 serves as tumor promoter in glioma cells through upregulating of Notch pathway, enhancing Hes-1 and NICD levels." (PMID 36229883, 2022). "Our analysis suggested that Notch signaling pathway (including key genes METTL3, DLL3, HES1, and NOTCH3) closely implicated with tumorigenesis and cancer development was found to be involved in glioma." (PMID 34589481, 2021). "The Notch1 signaling pathway proteins (Notch1, Hes1) were obviously elevated in high grade glioma tissues particularly in GBM tissues." (PMID 31382985, 2019). "Second, down-regulation of miR-145 and up-regulation of BNIP3 increased the protein expression of Notch1, Hes1, and p21 in glioma cells." (PMID 28977881, 2017). "First, up-regulation of miR-145 and knockdown of BNIP3 decreased the protein expression of Notch1, Hes1, and p21 in glioma cells." (PMID 28977881, 2017). "Another study has shown that miR-524-5p behaves as a tumor suppressor by negatively targeting Jagged-1 and Hes-1 in gliomas." (PMID 29221202, 2017). "Notch1 and Hes1 have been demonstrated to be important oncogenes playing critical roles in glioma cell survival and TMZ resistance." (PMID 27894350, 2016). "Notch signaling blockade by γ-secretase inhibitors reduced proliferation of glioma cancer stem cells while decreasing Hes1 mRNA levels." (PMID 28018177, 2016). "Recently, it has been described that miR-524-5p can modulate the Notch signaling pathway by directly targeting Jagged-1 and Hes-1 in glioma." (PMID 25275294, 2014). "CNTN2 has been shown to promote glioma stem-like cell proliferation through regulation of EGFR-, HES1-, and APP/AICD-associated signaling pathways, and its knockdown suppresses tumor cell growth in vitro, supporting a functional role in glioblastoma progression." (PMID 41596752, 2026). "We assessed whether the response of different glioma cell lines to 2OHOA might be related to their basal HES1 expression." (PMID 39400678, 2025). "Moreover, in glioma cells, HES1 was found to bind to a panel of HES6-regulated genes, and HES1 expression was reduced after HES6 downregulation." (PMID 35673577, 2022). "METTL3 can activate Notch pathway and facilitate glioma occurrence through regulating its direct targets NOTCH3, DLL3, and HES1, and Notch pathway genes may serve as the potential treatment targets for glioma." (PMID 34589481, 2021).
glioma (continued). "The upregulation of Notch ligand JAG1 and targets Hey1, Hey2, Hes1 in brain tissues of glioma patients compared to that of healthy brain tissues also highlight the Notch signaling pathway as a potential therapeutic target in glioma patients." (PMID 33381038, 2020). "Furthermore, immunohistochemical (IHC) staining of Notch1 and Hes1 proteins were performed on 35 paraffin-embedded high grade glioma samples (15 cases anaplastic astrocytoma and 20 cases GBM) and 12 control brain samples." (PMID 31382985, 2019). "Moreover, the proliferation of CD133+ glioma stem cells measured by clone formation is significantly inhibited after transfection with shRNA targeting Hes1." (PMID 28881855, 2017). "Collectively, these findings and other previous report demonstrated that METTL3 can activate Notch pathway and facilitate glioma occurrence through regulating its direct targets NOTCH3, DLL3, and HES1, and Notch pathway genes may serve as the potential treatment targets for glioma." (PMID 34589481, 2021). "From other findings and our cell experiment results, we demonstrated that METTL3 can activate Notch pathway and facilitate glioma occurrence through regulating its direct targets NOTCH3, DLL3, and HES1, and Notch pathway genes may serve as the potential treatment targets for glioma." (PMID 34589481, 2021). "Concurrently, γ-secretase inhibitor MK-0752 downregulates Notch1/Hes1 signaling, reducing AKT/mTOR phosphorylation and CXCR4 expression, thereby attenuating glioma stem cell aggressiveness." (PMID 40755759, 2025). "The miR-30c inhibitor enhanced the Notch1, NICD, HES1 and HEY1 proteins in A172 and U251 glioma cells, and shRNA-Notch1 weakened this enhancement." (PMID 36180477, 2022). "Linc-OIP5 overexpression enhances glioma tumorigenesis through Notch activation, upregulating JAG1, Notch-1 and Hes1 expressions." (PMID 36229883, 2022). "When the inhibitor was transfected into glioma cells, the expression levels of the Notch1, NICD, HES1 and HEY1 proteins in the inhibitor group were significantly higher than those in the inhibitor NC group (P < 0.05)." (PMID 36180477, 2022). "PlncRNA-1 overexpression induces glioma progression through boosting expressions of Notch1, JAG1 and Hes1, stimulating Notch signal." (PMID 36229883, 2022). "Of note, since MRK003 treatment caused a severe suppression in Hes1/Hey1 expression in some of the studied cells, we acknowledge that the proposed biomarkers may only be used to monitor glioma cells ́ responsiveness to BRON, but their blockade does not explain the impaired cell invasion." (PMID 33004830, 2020). "Next, we demonstrated that transcript levels of NOTCH pathway members NOTCH1, NOTCH4, DLL1 and HES-1, which carry METTL3-dependent m6A peaks, were downregulated in METTL3-silenced glioma cells." (PMID 30781903, 2019). "Further study demonstrated that after treating glioma U87 and U128 cells with TIG, the miRNA-199b-5p level obviously increased and the level of HES family BHLH transcription factor 1 (HES1), a target of miRNA-199b-5p, obviously decreased." (PMID 27994551, 2016). "Glioma cells treated with TMZ exhibited significant increases in MGMT, Notch1 and Hes1 mRNA, and protein levels." (PMID 27894350, 2016). "To address if the NOTCH pathway was active in our glioma cell lines, we analyzed the gene expression profile of NOTCH receptors (NOTCH1-4), ligands (DLL 1,3,4 JAG 1,2) and target (HES1, HEY1,2) genes." (PMID 27183910, 2016). "Similar results were obtained using the U87 human glioma cell line, suggesting that indeed, ABCG2 regulation of stem cell marker gene expression (other than Hes1) can be mediated by MEF." (PMID 27456282, 2016). "Seventeen genes represent active Notch signaling components, including NOTCH1, NOTCH3, HES1, MAML1, DLL-3, and JAG2, which are enriched in the proneural subtype of glioma stem cells." (PMID 26599017, 2015).
glioma (continued). "METTL3 was positively associated with DLL3, HES1, and NOTCH3 expressions in the CGGA glioma dataset, but not the GSE16011 glioma dataset (0.23 < cor < 0.34, p < 0.05)." (PMID 34589481, 2021). "Furthermore, Notch1, Hes1 and CXCR4 expressing cells colocalized with or adjacent to the Nestin expressing glioma cells." (PMID 31382985, 2019). "We found that Notch1 and Hes1 were significantly upregulated in TMZ-treated glioma cells, but not in the combination of TMZ and GANT61-treated glioma cells." (PMID 27894350, 2016).
pancreatic cancer (30 papers, 2012 to 2025). "The target gene of the Notch pathway HES1 is also commonly overexpressed in premalignant lesions as well as tumors of the pancreas and bile ducts and is furthermore associated with poor survival." (PMID 33498866, 2021). "HES1 expression was significantly upregulated in pancreatic cancer tissues and correlated with poor prognosis, while HEY1 was also identified as a prognostic biomarker." (PMID 41200204, 2025). "For instance, MYEOV upregulation is linked with undesirable survival outcome of pancreatic cancer, which elevates the HES1 expression and triggers pancreatic cancer progression through enhancing SOX9 trans-activity." (PMID 35662734, 2022). "HES1 is a known target of notch signaling that has been shown to increase pancreatic cancer cell migration and invasiveness." (PMID 35451603, 2022). "in pancreatic cancer models to show that the small molecule HES1 inhibitor JI130 inhibits growth of human FN‐RMS tumor cells and xenografts." (PMID 36037042, 2022). "Mechanistic investigations revealed that SNGH7 interacted with Notch1 to regulate the stemness and Folfirinox resistance through the Notch1/Jagged1/Hes-1 signaling pathway in pancreatic cancer." (PMID 34631547, 2021). "In conclusion, our findings show that MSCs increased SNHG7 expression in pancreatic cancer cells, promoting the stemness and Folfirinox resistance via the Notch1/Jagged1/Hes-1 signaling pathway." (PMID 34631547, 2021). "In a word, our study revealed that HCG11/miR-579-3p/MDM2 acted as a ceRNA network to promote the progression of pancreatic carcinoma by activating Notch/Hes1 pathway, further affirming the importance of MDM2/Notch/Hes1 in pancreatic carcinoma." (PMID 34230221, 2021). "In conclusion, the pivotal observations in this study illustrated that HCG11 increased the expression of MDM2 via competitively targeting miR-579-3p to promote the Notch/Hes1 pathway, thereby promoting the progression of pancreatic carcinoma." (PMID 34230221, 2021). "Although this report is in pancreatic cancer, specific targeting of the HES1-repressive complex can also be applied to many other diseases, including CRC." (PMID 32630477, 2020). "Previous work in pancreatic cancer has showed that deletion of Lfng in a KrasLSL‐G12D mouse model upregulates Notch3 and Hes1, accelerating cell proliferation." (PMID 29193607, 2018). "In vitro studies, applying a COX-2-selective inhibitor to COX-2-positive pancreatic cancer cells, revealed that expression of Notch1, Hes1 and DLL1 depended on COX-2-mediated prostaglandin synthesis." (PMID 27381829, 2016). "Incubation of pancreatic cancer tumorspheres with increasing doses of GSI reduced expression levels of the Notch target gene Hes1 in a dose dependent manner (p<.001 vs. control)." (PMID 24647545, 2014). "Inhibition of the Notch pathway using either a gamma secretase inhibitor or Hes1 shRNA in pancreatic cancer cells reduced the percentage of CSCs and tumorsphere formation." (PMID 24647545, 2014). "We uncovered that, upon its release, NIC1 undergoes hierarchical phosphorylation in pancreatic cancer cells that correlates with expression of NOTCH target genes such as HES1." (PMID 24392017, 2013). "MYEOV promotes pancreatic cancer progression by increasing HES1 expression and SOX9 transactivity." (PMID 35077391, 2022). "MSCs could increase the expression of SNHG7 in pancreatic cancer cells, which would promote the dryness and Folfirinox resistance of pancreatic cancer cells through the Notch1/Jagged1/Hes-1 signaling pathway." (PMID 35281017, 2022). "Some studies have shown that Hes1 is highly expressed in pancreatic cancer cells." (PMID 34476005, 2021). "Finally, our findings showed that MSCs increased SNHG7 expression in pancreatic cancer cells, promoting the stemness and Folfirinox resistance via the Notch1/Jagged1/Hes-1 signaling pathway." (PMID 34631547, 2021).